RAF1 (Raf-1 proto-oncogene, serine/threonine kinase)
Diseases named in the same sentence as RAF1 in open-access papers (continued):
Sharing a sentence is not in itself a finding about the gene and the disease.
cancer (continued). "We further knocked down v-raf-1 murine leukemia viral oncogene homolog 1 (RAF1), an upstream regulator gene of the MEK signaling pathway, using shRNA to see whether the compound cytotoxicity or induction of vacuole formation in cancer cell cytoplasm was affected." (PMID 28915644, 2017). "Therefore, further research on the ubiquitination sites of Raf-1 regulated by E3 ligases or USP7 is expected to modulate the ERK1/2 signaling pathway by selectively regulating the stability or activity of Raf-1, which could be a new therapeutic strategy in the ERK1/2 cascade activated cancers." (PMID 35948545, 2022). "We speculate that small-molecule inhibitors and/or antagonists targeting Ras and Raf-1 at domains and/or regions that are not required to form the Ku70-Ras-Raf signalosome might be beneficial in controlling the development and/or progression of cancers with hyperactivated Ras-ERK signaling." (PMID 38277448, 2024). "We identified new gene fusions involving ROS1, SLC1A2, RAF1, EWSR1, CDK6, and CLTC, some occurring in cancer types not previously known to harbor fusions." (PMID 23637631, 2013).
infection (148 papers, 2009 to 2025). The state of being infected such as from the introduction of a foreign agent such as serum, vaccine, antigenic substance or organism. "The ratio of co-precipitated 14-3-3 and Flag-fused RAF1 is indicative of their relative association during infection." (PMID 39902964, 2025). "Consistent with this, RAF1 associates with 14-3-3 during infection, which can be substantially reduced by the S621A mutation or by Compound C treatment." (PMID 39902964, 2025). "The co-precipitated 14-3-3:Flag ratio was reduced when the RAF1-S621A allele was expressed during infection, suggesting reduced 14-3-3 association, which is consistent with previous reports indicating that S621 phosphorylation is important for 14-3-3 binding (40, –, 44)." (PMID 39902964, 2025). "To further test the impact of RAF1 inhibition on the replication of another HCMV strain, we targeted RAF1 during TB40/E infection in fibroblasts and epithelial cells." (PMID 39902964, 2025). "infection led to increased expression of raf1, rhoA, akt, indicating activation of intracellular signaling pathways involved in inflammation and tissue remodeling." (PMID 40740775, 2025). "Collectively, these data suggest that the activity of RAF1 is reduced at later times during infection." (PMID 39902964, 2025). "At 72 h post-infection, the Flag-fused RAF1 proteins were purified via Flag-antibody affinity and analyzed for co-precipitation with 14-3-3." (PMID 39902964, 2025). "We, therefore, assessed the interaction between RAF1 and 14-3-3 during infection in the absence or presence of the AMPK inhibitor, Compound C (CC)." (PMID 39902964, 2025). "We demonstrate that ERK1/2, NF-κB and the MAP3K Raf1 were indispensable for EGR1 induction during infection, demonstrating for the first time a role for Raf1 signalling in epithelial cell responses to C. albicans infection." (PMID 39635778, 2024). "The addition of Compound C during infection resulted in less negatively charged RAF1, shifting the RAF1 isoforms toward the more basic (pH 10.0) cathode and suggesting substantially decreased phosphorylation, although not back to the same position of mock-infected cells." (PMID 39902964, 2025). "The total levels of RAF1 also fall over the course of infection." (PMID 39902964, 2025). "Notably, RAF1 levels dropped by approximately 50% relative to mock at 24 h post-infection (hpi) and remained there until 48 hpi, then decreased further as infection progressed." (PMID 39902964, 2025). "However, we observed that RAF1 KO in MRC5 cells reduced viral titers relative to parental cells at 120 h post-infection." (PMID 39902964, 2025). "While the overexpression of either RAF1-WT or RAF1-S621A increased the downstream phosphorylation of RAF1 targets, including MEK and ERK, we wanted to determine if the expression of these RAF1 variants differentially impacted infection." (PMID 39902964, 2025). "However, the functional relevance of potentially reduced RAF1 activity to infection is unclear." (PMID 39902964, 2025). "Additionally, raf1, a MAPKKK involved in Ras-dependent signaling, has been linked to thrombocyte activation and cellular survival pathways, suggesting an ancillary role in coordinating immune and metabolic cues at the infection site." (PMID 40740775, 2025). "After infection at an MOI of 0.05 and incubation for 10 days, the number of GFP-positive cells was significantly lower in the RAF1 KO cells." (PMID 39902964, 2025). "At early times post-infection, HCMV increases the levels of S338 phosphorylated RAF1, consistent with its activation." (PMID 39902964, 2025). "Here, our data suggest that AMPK phosphorylates RAF1, a central MAPK signaling component that we find is important for infection." (PMID 39902964, 2025). "As the duration of infection prolonged, the expression levels of MsDC-SIGN, RAF1, and IL10 remained significantly down-regulated even after 12 h of stimulation in contrast to the group that did not undergo RNA interference." (PMID 38732232, 2024).
infection (continued). "Together, these studies showed that MeV avoids RLR activation by preventing both RIG-I and MDA5 dephosphorylation in a Raf1-dependent manner during early infection, and the MDA5 dephosphorylation in a protein V-dependent manner in the late infection." (PMID 38267954, 2024). "The FAM168B, RAF1, HESX1, USP8, C2CD5, PIGC, ENSGALG00000053041, and ENSGALT00000092369 were found to be top driver genes shared among dpi, body weight post-infection, and propionate and valerate cecal contents." (PMID 36902251, 2023). "One possibility is that pharmaceutical-mediated RAF1 inhibition is more complete, that is, residual RAF1 activity could be present upon shRNA and CRISPR-mediated RAF1 inhibition and thus support infection to a greater extent than pharmaceutical inhibition." (PMID 39902964, 2025). "The modest impact of RAF1 inhibition on immediate early gene expression at the start of infection suggests that RAF1 activity is not necessary for viral entry; rather, it indicates that RAF1 is important for post-entry early events of infection leading to DNA replication." (PMID 39902964, 2025). "Raf-1 also contributes to infection by Japanese encephalitis virus, and a Raf-1-targeting ASO could reduce viral propagation and inhibit virus spread from the periphery to the brain in a mouse model of infection with JEV." (PMID 34959297, 2021). "Although total RAF1 levels were marginally higher with Compound C treatment compared to DMSO control at each time point, they were not fully restored to mock or early infection levels." (PMID 39902964, 2025). "During infection, the CRISPR-mediated inactivation of RAF1 in the MRC5 cells did not impact the accumulation of viral protein, UL26." (PMID 39902964, 2025). "Accordingly, VP1/VP2 heterotrimers expressed in insect cells, which are devoid of Raf-1, failed to enter the nucleus and Raf-1 expression correlated with cell permissiveness to MVM infection." (PMID 28974036, 2017).
genetic disorders (6 papers, 2014 to 2024). "Raf1 phosphorylation on serine 259 contributes to control the mitogenic response induced by MAPK signaling, and it has been observed in the context of genetic disorders." (PMID 25905717, 2015).
neurological disease (5 papers, 2014 to 2025). "Among these various interacting genes, four (RAF1, BRD4, ATRX, and TKT) have been associated with syndromic congenital conditions involving craniofacial abnormalities, heart defects, and neurological disorders." (PMID 40525707, 2025).
cardiac disease (3 papers, 2016 to 2024). "Mutations in the RAF1 CR1 functional domain, reported in multiple large-scale heart disease cohorts, may be associated with the disease." (PMID 38952713, 2024).
cardiovascular diseases (3 papers, 2018 to 2025). "Genomic test identified variants of uncertain significance in the TTN, MYH11, and RAF1 genes, which are associated with cardiovascular diseases but not directly linked to AF." (PMID 40625395, 2025). "The NF-kB signaling pathway is also observed with molecules EGFR, INSR, RAF1 and IGF1R involved in the pathway, this pathway is involved in cardiovascular disease and angiogenesis." (PMID 37569355, 2023).
CNS tumors (3 papers, 2018 to 2024). "Furthermore, all RAF1 fusion proteins identified in pediatric CNS tumors have N-terminal partners that possess a coiled-coil or other dimerization domain, meaning they belong to type I of kinase fusions." (PMID 35169893, 2022). "RAF1 has at least six different fusion partners in pediatric CNS tumors (Online Resource 3)." (PMID 35169893, 2022).
inflammation (1 paper, 2008). Aberrant reaction of the microcirculation characterized by movement of fluid and leukocytes from the blood into extravascular tissues. "Dexamethasone and a Raf-1 inhibitor are both able to suppress smoke-induced airway inflammation and hyperreactivity." (PMID 18976506, 2008).
retinopathy (1 paper, 2007). "The therapies that inhibited the development of retinopathy in diabetic rats also inhibited Raf-1 activation." (PMID 17515880, 2007).
vasculopathy (1 paper, 2024). "The state of knowledge of its role in vasculopathy brain changes is less consolidated but there are evidences in Raf1 homozygous knock out mouse endothelial cells of the direct critical role of Raf1 in angiogenesis." (PMID 38874808, 2024).
RAF1 also shares sentences with these, for which no sentence is quoted: ZIKV infection (44 papers); dengue (41); Flavivirus Infections (11); endometrial cancer (5); osteoarthritis (5); encephalitis (4); Noonan syndrome 5 (4); adenocarcinoma (3); ampulla of Vater (3); esophageal squamous cell carcinoma (3); renal carcinoma (3); angiosarcoma (2); Anxiety (2); Burkitt lymphoma (2); CHARGE syndrome (2); ciliopathy (2); Dengue hemorrhagic fever (2); ganglioglioma (2); hairy cell leukemia (2); infiltrating ductal carcinoma (2); Japanese encephalitis (2); LEOPARD syndrome 2 (2); metabolic disease (2); metastatic cancer (2); microcephaly (2); myeloid leukaemia (2); neuroendocrine neoplasm (2); neurofibromatosis (2); neurofibromatosis type 1 (2); prostate adenocarcinoma (2).
A further 132 diseases each share a sentence with RAF1 in 2 papers or fewer.